IL27 (interleukin 27)
Diseases named in the same sentence as IL27 in open-access papers (continued):
Sharing a sentence is not in itself a finding about the gene and the disease.
heart disease (5 papers, 2018 to 2025). "Low levels of STAT phosphorylation in response to IL-27 in subjects with heart disease were associated with increased constitutive STAT phosphorylation and increased constitutive gene expression of these transcription factors." (PMID 34061845, 2021). "It has been shown experimentally that the administration of IL-27 improves the response of Th1 cells, both monofunctional and polyfunctional, in individuals without heart disease, along with an increase in the expression of IL-10." (PMID 39452741, 2024). "Trypanosoma cruzi-infected subjects without heart disease also showed decreased IL-27 levels in their circulation, further supporting the idea that IL-27 is consumed in a functional IL-27R axis." (PMID 34061845, 2021). "Addition of IL-7 or IL-27 in short-term cultures with T. cruzi antigens increased the number of IFN-γ-producing T cells in response to T. cruzi in IFN-γ producers but not IFN-γ nonproducers in patients with no signs of cardiac disease and patients with some degree of cardiac dysfunction." (PMID 30517089, 2018). "In contrast, in patients with heart disease (i.e., G1, G2/G3 groups), STAT phosphorylation did not significantly increase after IL-27 stimulation." (PMID 34061845, 2021). "Trypanosoma cruzi-infected subjects without heart disease (i.e., G0 clinical group) also showed an increased frequency of CD4+ and CD8+ T cells while expressing pSTAT3 or pSTAT5, but not pSTAT1, in response to IL-27." (PMID 34061845, 2021).
inflammation (5 papers, 2014 to 2022). Aberrant reaction of the microcirculation characterized by movement of fluid and leukocytes from the blood into extravascular tissues. "For instance, IL-30 gene therapy has been shown to efficiently inhibit autoimmune inflammation in the central nervous system (CNS) and eye, and lentiviral IL-27 gene delivery to the CNS inhibits neuroinflammation." (PMID 29740452, 2018). "Based on our data and our hypothetical model, IL27-induced endothelial inflammation is involved in the recruitment, adhesion, and infiltration of monocytes and of T cells." (PMID 26663990, 2015). "In summary, our results showing an increased expression of the innate immunity cytokine IL-27 in the bronchial mucosa of patients with stable COPD indicate its potential role in the progression of severity of chronic bronchial inflammation." (PMID 24430176, 2014).
Hematological disorders (2 papers, 2016). "Hematological disorders, such as hemoglobin concentration, negatively correlated with TNF-α, IL-6, IL-27 and IL-10 (all p ≤0.0005); Platelet and eosinophil counts were negatively correlated with TNF-α, IL-6, IL-27 and IL-10 (p ≤0.0005)." (PMID 26814478, 2016).
liver (2 papers, 2014 to 2023). "The lack of liver damage markers hindered our further analysis of HIV/HCV viral loads and IL-27 titers on liver damage progression." (PMID 24816922, 2014).
skin disorder (1 paper, 2020). Any deviation from the normal structure or function of the skin or subcutaneous tissue that is manifested by a characteristic set of symptoms and signs. "Altered concentrations of IL-27 have been shown in several autoimmune and skin disorders." (PMID 32616337, 2020).
IL27 also shares sentences with these, for which no sentence is quoted: acute myocardial infarction (4 papers); endothelial dysfunction (3); head and neck squamous cell carcinoma (3); heart failure (3); Hepatitis (3); leprosy (3); liver cirrhosis (3); liver fibrosis (3); pancreatitis (3); periodontitis (3); relapsing-remitting multiple sclerosis (3); renal cell carcinoma (3); unstable angina pectoris (3); acute lymphoblastic leukemia (2); autoimmune gastritis (2); bacterial pneumonia (2); cardiac hypertrophy (2); Chronic Hepatitis B (2); colon adenocarcinoma (2); dengue (2); fibrosis (2); glomerulonephritis (2); Graves orbitopathy (2); liver cancer (2); liver disease (2); metabolic disease (2); neuropathic pain (2); nonalcoholic fatty liver disease (2); viral diseases (2); -dependent (1).
A further 95 diseases each share a sentence with IL27 in 1 paper.